IL27 (interleukin 27)
Diseases named in the same sentence as IL27 in open-access papers (continued):
Sharing a sentence is not in itself a finding about the gene and the disease.
infection (continued). "Also, IL-27 was measured in serum samples from more than 95% of all individuals of the different infection groups with the exception of individuals with an egg load of 100 epg or more." (PMID 30619332, 2018). "Thus, in subsequent experiments we focused on examining the effects of IL-27 on the response to S. typhimurium components and infection." (PMID 30209294, 2018). "Having determined that IL-27 was elevated rapidly upon infection, we next investigated which cells might be responsible for its production." (PMID 29593047, 2018). "Similar results were obtained when mice treated between days -1 and 3 p.i. with αIL-6 were infected with mouse adapted H1N1 IAV PR8 (strain A/Puerto Rico/8/1934 H1N1), with IL-6 depleted mice showing delayed recovery from infection and reduced IL-6, IL-10 and IL-27 in the airways at day 10 p.i.." (PMID 28953978, 2017). "However, no increase in the RNA levels of IL-27p28 and EBI3 was detected in these cells 24 h after infection, suggesting that DCs, and not macrophages, are the main cell source responsible for the increase of IL-27 in our model." (PMID 27867384, 2016). "Neutralization of IL-27 in acutely infected BALB/c led to decreased parasite burdens and a transient increase in IFN-γ+ splenic T cells, while administration of IL-27 to C57BL/6 promoted a local anti-inflammatory cytokine response at the site of infection and increased parasite loads." (PMID 27867384, 2016). "However, a major role of IL-27 in infection is its suppression of excess immune responses against infection by controlling the production of pro-inflammatory cytokines." (PMID 26991425, 2016). "Thus, IL-27 plays an important role in immune response and pathogen clearance during infection with C. parapsilosis." (PMID 27259855, 2016). "Further analysis using a larger cohort of patients will help to better understand the value of IL-27 as a complementary biomarker for human VL diagnosis and even for treatment efficacy monitoring, as has been postulated for this disease and other infections." (PMID 27867384, 2016). "Productive infection of WT macrophages induced substantial IL-27 mRNA expression, peaking 6hrs pi." (PMID 27926930, 2016). "BALB/c, but not C57BL/6 mice, showed increased IL-27 systemic levels after infection, which was associated with an upregulation of IL-27p28 expression by dendritic cells and higher parasite burdens." (PMID 27867384, 2016). "Interactions with macrophage surface molecules, including the complement receptor, also plays a role in the activation of protein kinase regulated by RNA (PKR), which induces the release of IFNα, IL-27, and IL-10 among other cytokines that also modulate the host response to infection." (PMID 27148265, 2016). "Overall, we show that, as in humans, BALB/c IL-27 systemic levels are infection dependently upregulated and may favor parasite installation by controlling inflammation." (PMID 27867384, 2016). "However, at 16 days a modest impact of IL-27 on infection was observed with 73.8% of cells infected compared to controls (normalized to 100%; p=0.0116 t test)." (PMID 28058287, 2016). "Therefore, we next evaluated effects of IL-27 signaling on liver pathology during the course of infection with the parasites." (PMID 26222157, 2015). "Moreover, two recent adult studies have shown improved predictive values of IL-27 when excluding pulmonary sources of infection from the “infected” definition." (PMID 26514771, 2015). "A trend to improvement was noted, however, when a secondary analysis was performed by using a modified definition of infection that included only those patients found to have positive blood cultures, and IL-27 was found to have a significantly better predictive value when compared with PCT." (PMID 26514771, 2015). "IL-19, IL-10, IL-6, IL-27 and IL-5 also increased during late infection days." (PMID 26070790, 2015).
infection (continued). "Both, IL-27 and Foxp3, may occur in an infection scenario induced by Fh-KTM together with other molecules with redundant suppressor functions such as GST, CL1 or HDM." (PMID 25486609, 2014). "Thus, IL-27 plays an important role in limiting destructive inflammation, notably in the resolving phase of infection." (PMID 24809349, 2014). "The findings presented suggest that IL-27 is able to suppress cis-infection." (PMID 23527130, 2013). "Our data indicate that IL-27 may be one such cytokine that orchestrates Th1 cell conversion in vivo to reduce immune mediated pathology during infection." (PMID 23593003, 2013). "We conclude that IL-27 restricts the accumulation of pathogenic T cells in the liver during infection by co-ordinately suppressing soluble, non-chemokine, chemotactic signals and by repressing the development of highly migratory Th1 cells." (PMID 24244314, 2013). "We show that IL-27 both inhibits the migratory capacity of infection-derived CD4+ T cells towards infection-derived liver cells, but also suppresses the production of soluble liver-derived mediator(s) that direct CD4+ T cell movement towards the inflamed tissue." (PMID 24244314, 2013). "While the mechanisms remain unclear, the downregulation of IL17D or IL-27 (also downregulated in acute infection) might partially explain the reduced IL-8 expression observed later in infection." (PMID 22511950, 2012). "However, in murine models IL-27 has been shown to have anti-inflammatory effects in later stages of infection." (PMID 22761702, 2012). "IL-27 produced by myeloid cells has been shown not only to promote Th1 responses during an acute response to infection, but also to be required for damping of effector cell responses during the late adaptive stage of infection once the pathogen is controlled." (PMID 22479310, 2012). "The capacity for cDCs to drive polarization of IFNγ+IL-10+ cells may be as a result of their higher expression of IL-27 than CD11cint cells during infection." (PMID 22911108, 2012). "Indeed, the treatment with IL-12 and a soluble receptor for IL-27 during infection reduced the growth of bacteria recovered from macrophages." (PMID 21197399, 2011). "Furthermore, this clustering analysis highlighted that infection resulted in a loss of myeloid progenitors (cluster 7) that was further reduced in the absence of IL-27." (PMID 41396163, 2025). "Finally, we examined whether the immunity induced under IL‐27‐neutralizaion exhibit enhanced recall response against challenge infection." (PMID 37855243, 2023). "Thus, IL27 could play a novel host-defensive role to subvert viral inhibition of IFNs and possibly to take over infection control." (PMID 37310504, 2023). "Because HIV-1-infected cells are continuously exposed to a number of inflammatory mediators in the tissue microenvironment, regardless of how long they have been infected, we investigated whether IL-27 would keep its anti-HIV-1 effect if added later during the course of infection." (PMID 36602368, 2023). "However, IL-27 also promotes IL-10 production, (reviewed in a later section) which could downregulate IFNγ production later during infection to mediate immunopathology." (PMID 35634328, 2022). "In the context of experimental TB, IL-27 turns out to be a sheep in wolf’s clothing: Even though the cytokine significantly hampers optimal containment of Mtb in the lung, the cytokine eventually protects from pathological sequelae of chronic hyper-inflammation in the late stage of infection." (PMID 35116036, 2021). "Therefore, we speculated that the liver damage reduced by GdCl3 in the severe infection model may be related to the decrease in liver IL-27 levels, which may be related to the decrease of the M1 polarization proportion of liver macrophages." (PMID 33564275, 2021).
infection (continued). "Therefore, in order to take a deep insight into the role of liver macrophages in the severe infection model, further studies on the directly involvement of KCs and the direct relationship between IL-27 and KCs in this model and its mechanisms will be performed in the future." (PMID 33564275, 2021). "However, the levels of IL-27 in MP mixed infection group were significantly lower than those in MP single infection group and control, which suggested that IL-27 may be negatively related with other pathogens." (PMID 32393186, 2020). "In the present work, we hypothesized that increased levels of IL-27 predispose neonatal mice to more severe infection during Gram-negative sepsis." (PMID 31818960, 2020). "However, more recently IL-27 has also been shown to act as a negative regulator of ongoing immune responses during infection and autoimmune inflammation and under these circumstances IL-27 can limit pro-inflammatory cytokine production by CD4 T cells, including IFNγ." (PMID 30044874, 2018). "Together, these data highlight the critical role of IL-27 in enabling optimal antiviral immunity early and late after infection with a systemic persistent virus and suggest that a previously unrecognized positive-feedback loop mediated by IL-27 in pDCs might be involved in this process." (PMID 29593047, 2018). "Importantly, the new roles reported for IL-27 as a regulatory cytokine emerged from infection studies suggesting that IL-27 may also have important roles in fungal control." (PMID 29793796, 2018). "Taken together, these findings suggest that an IL-27 positive-feedback loop may contribute to maintenance of pDC numbers very early after infection and to IFN-I production from myeloid cells and that disabling such a loop could compromise peak IFN-I responses and virus control." (PMID 29593047, 2018). "Although it is still unclear whether IL-27 also regulates IL-10 expression by T cells during M. tuberculosis infection, IL-27Rα signaling in CD4+ T cells has been recently shown to confer susceptibility to this infection." (PMID 28584007, 2017). "IL-27 seems to be a key anti-inflammatory mediator in different inflammatory settings, including its relatively known role on the control of the liver immunopathology after T. congolense or T. cruzi infections and its suppressive effects on CD4 T cell subpopulations." (PMID 29033934, 2017). "Hence this mechanism that we propose may also contribute to the detrimental role of IL-27 during infection in addition to that suggested by others that IL-27 signaling impairs T cell fitness and protective function during M. tuberculosis infection." (PMID 28584007, 2017). "Furthermore, the infection phase may also influence the impact of IL-27 on IL-10+ T cell development." (PMID 27926930, 2016). "Therefore, this natural high expression of TLR-2 by BALB/c may favor the IL-27 increase early after infection, lowering inflammation, and promoting infection." (PMID 27867384, 2016). "In addition, IL-27 inhibits the development of inducible T regulatory cells (Tregs), whereas other studies show that IL-27 promotes the growth and survival of Tregs at local sites of infection." (PMID 27259855, 2016). "Therefore, downstream of IFN-γ, both IL-27 and IL-6 may be necessary to induce the maximum myelopoiesis to control infection." (PMID 26991425, 2016). "In addition to IL-27, type I interferon affects IL-10 production during infection." (PMID 25651926, 2015). "Despite having a modest predictive value for infection independent of source, IL-27 may serve as a useful biomarker in estimating risk of bacterial infection among critically ill pediatric patients with bloodstream infections." (PMID 26514771, 2015). "The findings uncover an important role of IL-27 in limiting the collateral damages of anti-viral immunity and provide initial evidence that these mechanisms might be exploited for the management of severe immunopathology after infection." (PMID 24809349, 2014).
infection (continued). "Interestingly, in the presence of robust IL-27 expression we also observed a greater induction of IL-10 in the serum of IL-27-expressing mice by day 7 post-infection compared to control or p28-expressing mice, while systemic IFNγ protein was similar between all groups." (PMID 22479310, 2012). "Thus, IL-27 was analyzed in the serum of both acute and chronically infected mice after infection." (PMID 22479310, 2012). "We quantified serum levels of IL-4, IL-6, IL-8/CXCL-8, IL-27, CCL-2, CXCL-9, CXCL-10, and IgG using Luminex and ELISA assays during the acute and subacute phases of infection." (PMID 40711072, 2025). "IL-12/IL-10 interaction is the line of balance in kala-azar: at the infection site, intracellular amastigote molecules drive the activity of the infected macrophages to promote a predominant IL-12/ IFN-γ or IL-10/IL-27 synthesis." (PMID 40732663, 2025). "Both strains augmented IL-27 (6 h) and only L. plantarum MPL16 increased IL-6 and IL-8 at 6 h post-infection." (PMID 41155369, 2025). "IL-27 concentrations were the most elevated in OVA-sensitized mice at 1 DPC and in primary infection mice at 7 DPC, time points that corresponded to peak inflammation and pathology." (PMID 41190814, 2025). "In fact, silencing the BST-2/Tetherin gene permitted IL-27 to function again as a potent HIV-1 inhibitory factor, similar to when BST2-sufficient infected PBMCs were exposed to this cytokine shortly after infection." (PMID 36602368, 2023). "Infection of MDMs with tubercle bacilli led to an increase in the concentration of most tested cytokines except CCL2 and IL-27." (PMID 37781389, 2023). "We found that BST2 silencing 2 h after infection abolished the IL-27-mediated increase in the expression of BST-2/Tetherin and, in addition, weakened the anti-HIV-1 effect of IL-27." (PMID 36602368, 2023). "In this study, IL-27 was responsible for reducing the levels of TNF and IFNγ required for parasite control, therefore favoring infection." (PMID 35384718, 2022). "On the other hand, this inflammatory response was more efficiently regulated in the later stages of the infection, as evidenced by decreased levels of neutrophils, TNF-α, CCL2, and IL-6 and the increases in the regulatory cytokines IL-10 and IL-27." (PMID 34207076, 2021). "Measuring the release of 54 inflammatory mediators confirmed the transcriptomic data and revealed sustained production of tolerogenic factors (IL-27, IL-10, IL-1RA, TSLP) despite infection." (PMID 34367171, 2021). "The L. donovani infection in BALB/c mice promotes IL-27 expression by splenic CD8α+ and CD4+ DCs on days 1, 14, and 28 post-infection." (PMID 32849534, 2020). "The lung homogenates of WT and AhR−/− mice were collected after 96 h, 2 and 10 weeks of infection and used to evaluate the presence of cytokines (IL-12, TNF-α, IL-1β, IL-6, IL-23, IL-2, IFN-γ, IL-4, IL-17, IL-22, TGF-β, IL-10, IL-27, and IL-35)." (PMID 32647342, 2020). "Collectively, IL-27 is expressed by different DC subsets during the early phase of L. donovani infection, IL-27 may directly and/or indirectly suppress the protective Th1 cell-mediated responses against L. donovani infection, which may delay the resolution of the parasite infection." (PMID 32849534, 2020). "• Infection promotes the IL-27 expression by splenic CD8α+ and CD4+ DC at days 1, 14, and 28 post-infection." (PMID 32849534, 2020). "Our data indicate that the lack of PD-L1 is associated with a lower production of IL-27 by monocytes infiltrating the lesion during the initial phase of infection, which might lead to a lower amount of CD4+Ly6Chi T effector cells and a diminished secretion of Th1 cytokines." (PMID 33193363, 2020). "Infection of mice with S. aureus-induced an early inflammatory cytokine response with high levels of IL-1α, IL-1β, IFN-β, TNF-α, IL-6, IL-12p70, IL-27, and IFN-γ in the spleen detected for up to 12 h pi compared to PBS-treated mice." (PMID 31134074, 2019).
infection (continued). "Given that IL-27 promoted the numbers of antiviral CD4 T cells upon infection, and specifically M09133-147 specific CD4 T cells, we reasoned that IL-27 signaling would also help control viral replication in the salivary glands." (PMID 30044874, 2018). "IL-27 and IFN-γ can also induce a Treg population (T-bet+, CXCR3+) that produce higher IL-10 to limit T effector responses, thus reducing infection-induced pathology." (PMID 29118754, 2017). "We demonstrate that IL-27 is critical for the induction of peripheral IL-10+CD4+ T cell responses and subsequent suppression of TH1 responses during the persistent phase of infection." (PMID 27926930, 2016). "Although after infection the production of IL-27p28 was greater in BMMØ from C57BL/6 than from BALB/c (p ≤ 0.05), IL-27 concentration was similar in both mouse strains." (PMID 27867384, 2016). "We exploited the IL-27 dichotomy in BALB/c and C57BL/6 mice to study the role of this cytokine during the early steps of infection, using an in vivo artificial-modulation approach." (PMID 27867384, 2016). "mRNA levels of both subunits of IL-27 (IL-27p28 and EBI3) were upregulated in the liver of mice at day 7 and 10 after infection, compared to uninfected mice." (PMID 26222157, 2015). "On multivariate regression, comparing cytokine gene expression in health and infection, IL10 (P = 0.02), IL23 (P = 0.01), IL27 (P = 0.01), and TNFα (P = 0.03) were significantly different." (PMID 23935244, 2013). "When healthy controls and patients with infection were compared, IL2 and IL23 gene expression was lower in patients with infection, and gene expression of IL10 and IL27 were greater in patients with infection." (PMID 23935244, 2013). "We also demonstrated that a combination of IL-27 and PCT improves the overall ability to predict infection, compared with that of either biomarker alone." (PMID 23107287, 2012). "IL-27 plays a role in the development of IFNγ+IL-10+ CD4+ T cells during experimental L. major and Listeria monocytogenes infection in vivo, as assessed using IL-27Rα−/− mice." (PMID 22911108, 2012). "Thus, while we now show that IL-27 secretion by APCs can be modulated through ligation of the PILRα and PILRβ receptors, we cannot eliminate the possibility that IL-10 may also contribute to the increased survival we observed after peroral infection." (PMID 22479310, 2012). "Collectively, these data demonstrate that a combination of IL-27 and PCT improves the overall ability to predict infection in this cohort of critically ill patients, compared with either biomarker alone." (PMID 23107287, 2012). "Late infection featured further Th1 reduction, neutrophil accumulation, and NETs activation (H3cit, NE-DNA, MPO), along with reduced CXCL9 but elevated IL-6, IL-21, IL-27, CXCL10, and S100A8 in blood." (PMID 42112327, 2026). "Early infection was marked by elevated lung CD4+ T cells (Th17/Treg), diminished Th1 cells and neutrophils, and increased blood cytokines (IFN-γ, IL-21, IL-6, IL-27)." (PMID 42112327, 2026). "Administration of exogenous IL-27 reduced soft tissue abscesses and peri-implant bone resorption during infection; however, this effect was observed in wild-type mice but not in IL-27Rα-/- mice." (PMID 40724937, 2025). "This enhanced monocyte differentiation appeared independent of IFN-γ, as blockade of IL-27 during infection in IFN-γ reporter mice showed no alteration in cytokine levels in the bone marrow." (PMID 41396163, 2025). "In the absence of infection, the fetuses of IL-27-neutralized and IL27RA−/− dams exhibited healthy outcomes and no observable pathology at E13.5." (PMID 40502752, 2025). "Infection with T. gondii leads to increased production of monocytes that is enhanced in the absence of IL-27, but it is unclear if this is a result of differentiation from HSPCs or from the more differentiated monocyte progenitors (MPs)." (PMID 39868131, 2025).